TMEM88 (transmembrane protein 88)
Description:
Inhibits the Wnt/beta-catenin signaling pathway. Crucial for heart development and acts downstream of GATA factors in the pre-cardiac mesoderm to specify lineage commitment of cardiomyocyte development.
Synonyms: MGC71744; FLJ20025
Tractability: Antibody: UniProt places it where antibodies can reach, with high confidence; its Gene Ontology location is reachable by antibodies, with high confidence; UniProt predicts a signal peptide or a membrane-spanning region.
Gene: Protein-coding gene on chromosome 17 (7,855,059 to 7,856,114, forward strand). Ensembl gene ENSG00000167874.
Subcellular location: Cell membrane
Gene Ontology:
Molecular function: protein binding; PDZ domain binding
Biological process: negative regulation of canonical Wnt signaling pathway; protein localization to plasma membrane; protein stabilization
Cellular component: cytosol; plasma membrane
Genetic constraint (gnomAD): Loss-of-function variants: 8 observed, 7.73 expected, observed/expected ratio (o/e) 1.04, 90% interval 0.6 to 1.75. That is too few expected variants to judge how well the gene tolerates losing a copy. Missense variants: 255 observed, 199.26 expected, observed/expected ratio (o/e) 1.28, 90% interval 1.15 to 1.42. Synonymous variants: 139 observed, 95.78 expected, observed/expected ratio (o/e) 1.45, 90% interval 1.26 to 1.67.
Homologues: Orthologues: chimpanzee TMEM88 (100% identical), macaque TMEM88 (97% identical), pig TMEM88 (96% identical), rabbit TMEM88 (95% identical), dog TMEM88 (94% identical), guinea pig TMEM88 (89% identical), mouse Tmem88 (89% identical), rat Tmem88 (82% identical).
Diseases named in the same sentence as TMEM88 in open-access papers:
TMEM88 is named in the same sentence as 32 diseases in open-access papers, as found by Europe PMC text mining. Sharing a sentence is not in itself a finding about the gene and the disease. The quoted sentences say what the papers report.
ovarian carcinoma (10 papers, 2018 to 2024). A malignant neoplasm originating from the surface ovarian epithelium. "TMEM88 has also been found to be associated with increased resistance to platinum in ovarian cancer." (PMID 37561335, 2024). "TMEM88 is a transmembrane protein that functions as an inhibitor of Wnt signaling, and TMEM88 promoter hypomethylation is associated with platinum resistance in ovarian cancer." (PMID 34184409, 2021). "Indeed, promoter hypermethylation of TMEM88 is associated with poorer prognosis of non-small cell lung cancer, whereas the hypomethylation is associated with platinum resistance in ovarian cancer." (PMID 35126454, 2021). "TMEM88 overexpression inhibited cells proliferation, and enhanced the sensitivity of ovarian cancer to DDP." (PMID 38850316, 2024). "For example, in ovarian cancer, lower methylation levels of TMEM88 were observed in platinum-resistant xenografts compared to platinum-sensitive ones." (PMID 37091140, 2023). "Analysis of the transcriptome information of ovarian cancer patients in the TCGA database shows that TMEM88 is closely correlated with the mRNA expression levels of c-Myc and β-catenin mRNA (P = 0.01252 and 0.0128)." (PMID 35734592, 2022). "At present, abnormal changes in TMEM88 have been found in breast cancer, ovarian cancer, lung cancer, thyroid cancer and other malignant tumors, which has also attracted the attention of tumor research and attempted to clarify its function and mechanism." (PMID 35734592, 2022). "Meanwhile, the application of the DNA methyltransferase inhibitor SGI-110 can significantly increase the TMEM88 mRNA level and corresponding protein expression in platinum-sensitive ovarian cancer cells." (PMID 35734592, 2022). "Hypomethylation of developmental genes MSX1 and TMEM88 correlated with platinum resistance in patients with ovarian cancer." (PMID 31608277, 2019). "Hsa-miR-708 acts as an oncogene in lung cancer by downregulating TMEM88, but was reported to suppress ovarian cancer metastasis through targeting Rap1B." (PMID 29755664, 2018). "The hypomethylation of TMEM88 promoter observed in ovarian cancer led to an increased expression of the protein and to platinum resistance." (PMID 30574087, 2018). "Interestingly, knockdown of TMEM88 in ovarian cancer cells enhanced cell proliferation but also resensitized them to platinum treatment, highlighting the potential role of TMEM88 in restoring therapeutic sensitivity in tumors." (PMID 37091140, 2023). "Interestingly, although knockdown of TMEM88 enhanced ovarian cancer cell proliferation, it also re-sensitized cells to platinum treatment." (PMID 37091140, 2023). "First of all, TMEM88 downregulation led to an increase in Wnt target gene expression such as β-catenin or Jun, validating the interaction between TMEM88 and Wnt pathway in ovarian cancer." (PMID 30574087, 2018).
lung carcinoma (7 papers, 2016 to 2024). "Subsequently, researchers used 5-aza-2’-deoxycytidine (DAC) to treat A549 and H1299 cells to further evaluate the functional alterations of TMEM88 methylation in lung cancer." (PMID 35734592, 2022). "Kaplan-Meier survival analysis showed that the overall survival of lung cancer patients (38.8 ± 4.83 months) with high TMEM88 expression was significantly lower than that of patients (58.64 ± 4.24 months) with low TMEM88 expression." (PMID 35734592, 2022). "It acts as an oncogene by contributing to tumor growth and disease progression through downregulation of TMEM88 in lung cancer." (PMID 27092874, 2016). "Furthermore, certain methylation markers, such as DAL-1, EPHB6, HS3ST2, TMEM88 and MGMT, specifically associated with lung cancer progression and metastasis, were found to have increased methylation levels." (PMID 37506102, 2023). "Based on these data, it is impossible to conclude whether miR-708-5p pro-oncogenic effects on lung cancer cells are through TMEM88." (PMID 29050362, 2017). "A549 and H1299 lung cancer cells have high levels of cytoplasmic TMEM88, which did not contribute to proliferation, but did promote metastasis in vivo." (PMID 29050362, 2017).
breast carcinoma (4 papers, 2015 to 2023). "The results showed that the overall expression level of TMEM88 in breast cancer tissues (71.22%, 99/139) was significantly higher than that in normal tissue (11.4%, 4/35; P < 0.001), and the specific expression differences were not the same." (PMID 35734592, 2022). "The normalized expression level of the 17-kDa TMEM88 isoform in breast cancer tissues (mean ± SD:1.019 ± 0.697) was significantly higher than that in the paired noncancerous tissues (mean ± SD:0.579 ± 0.408; p = 0.011)." (PMID 26325443, 2015). "Our results indicate that cytosolic TMEM88 enhances breast cancer cell invasion, and that this process is dependent on the interaction between TMEM88 with Dvl proteins." (PMID 26325443, 2015). "We explored the potential mechanism by which cytosolic TMEM88 stimulates breast cancer cell invasion by examining the expression levels of the proteins involved in the EMT." (PMID 26325443, 2015). "We next evaluated the expression levels of TMEM88 in 16 fresh breast cancer samples by western blot analysis." (PMID 26325443, 2015). "In contrast, cytosolic TMEM88 expression was significantly higher in breast cancer tissues (54.67%, 76/139) than in carcinoma in situ specimens or in normal breast ductal tissues." (PMID 26325443, 2015). "To examine the biological roles of cytosolic TMEM88 in breast cancer cells, we transfected MCF-7 with vectors expressing TMEM88 and TMEM88-ΔC (a TMEM88 variant that is unable to interact with Dvl)." (PMID 26325443, 2015). "In summary, TMEM88 was highly expressed in both breast cancer tissues and cell lines and primarily exhibited cytoplasmic localization in these tissues." (PMID 26325443, 2015). "In our study, only three specimens harvested from breast cancer patients exhibited membrane localization of TMEM88." (PMID 26325443, 2015). "As a result, comparing with normal tissues, TMEM88 was significantly decreased in bladder cancer, breast cancer, cervical cancer, colon cancer, rectum cancer, kidney chromophobe cancer, kidney renal papillary cell carcinoma, NSCLC, prostate cancer, and uterine corpus endometrial carcinoma." (PMID 37091140, 2023). "In both the overall breast cancer specimens and the triple-negative breast cancer specimens, cytosolic TMEM88 localization correlated positively with both lymph node metastasis (p = 0.01 and p = 0.002, respectively) and tumor node metastasis (TNM) stage (p = 0.038 and p < 0.001, respectively)." (PMID 26325443, 2015). "Furthermore, by modulating the expression levels of TMEM88, we assessed the role of this protein in the proliferation and metastasis of breast cancer cells." (PMID 26325443, 2015). "Western blot analyses indicated that TMEM88 promoted Snail expression and inhibited Zo-1 and Occludin expression by interacting with dishevelled (Dvl) proteins, thereby stimulating invasion and metastasis in breast cancer." (PMID 26325443, 2015). "Furthermore, MDA-MB-231 cells were transfected with a control or TMEM88-specific siRNA to assess the effects of TMEM88 silencing in breast cancer cells." (PMID 26325443, 2015). "Immunohistochemic alanalysis of 139 breast cancers pecimens(64 triple-negative cancers and 75 non-triple-negative cancers) indicated that TMEM88 is expressed at significantly higher levels in breast cancer tissues (71.22%, 99/139) than in normal breast tissues (11.4%, 4/35; p < 0.001)." (PMID 26325443, 2015). "Indeed, characterization of the biological roles of the distinct subcellular localization patterns of TMEM88 may provide new insights into targeted therapy for breast cancer." (PMID 26325443, 2015).
triple-negative breast carcinoma (4 papers, 2015 to 2024). An invasive breast carcinoma which is negative for expression of estrogen receptor (ER), progesterone receptor (PR), and human epidermal growth factor receptor 2 (HER2). "Studies have found that the competitive combination of TMEM88 and disheveled inhibited the activation of the Wnt/β-catenin pathway, thereby inhibiting the progression of triple-negative breast cancer." (PMID 38850316, 2024). "The cytosolic and nuclear expression rates of TMEM88 were 57.81% and 9.37% in triple-negative and 52% and 33.33% (p = 0.5 and p = 0.001) in the non-triple-negative breast cancer tissues, respectively." (PMID 26325443, 2015). "In contrast, nuclear localization of TMEM88 was negatively correlated with lymph node metastasis in triple-negative breast cancer, implying that TMEM88 may play completely distinct tumor-related roles relying on its subcellular localization." (PMID 37091140, 2023). "Although TMEM88 is normally localized in cell membrane, Zhang’s data and Yu’s data suggested that cytosolic mislocalization of TMEM88 promotes the progression of NSCLC and triple-negative breast cancer, respectively." (PMID 37091140, 2023).
bladder cancer (3 papers, 2022 to 2023). "A study in bladder cancer found that overexpression of TMEM88 also inhibited the activation of the Wnt/β-catenin signaling pathway by reducing the phosphorylation level of GSK-3β (Ser9 site)." (PMID 35734592, 2022). "In vitro, depletion of TMEM88 in bladder cancer cells, such as UM-UC-3 and T24 cells, can enhance their invasive and proliferative capacity, while restoring TMEM88 levels can reverse these effects." (PMID 35734592, 2022). "In the detection of 6 bladder cancer patient tissues, it was found that the expression of TMEM88 in patient tissues indeed showed a downward trend compared with adjacent normal tissues." (PMID 35734592, 2022). "In in vivo experiments in nude mice, overexpression of TMEM88 exhibited a certain inhibitory action on bladder cancer cell growth and tumor formation." (PMID 35734592, 2022). "Consistently, TMEM88 upregulation can result in the decreased ability of cell proliferation and invasion dramatically in bladder cancer, and nude mouse models substantiated that the overexpression of TMEM88 prevents tumor formation and growth of bladder cancer cells." (PMID 37064154, 2023). "Moreover, the study conducted bioinformatic analysis of the GEPIA2 and ENCORI databases and found that the expression of TMEM88 in bladder cancer tissues was significantly reduced compared to that in normal tissues." (PMID 35734592, 2022). "The in vivo xenograft experiments further validated the anti-tumor effects of TMEM88 in HCC, which is consistent with previous findings in bladder cancer." (PMID 37091140, 2023).
hepatocellular carcinoma (3 papers, 2023 to 2025). A malignant tumor that arises from hepatocytes. "However, the expression, function, and prognostic significance of TMEM88 in hepatocellular carcinoma (HCC) remain unclear." (PMID 37091140, 2023). "A recent investigation reported that the TMEM88 protein is downregulated in hepatocellular carcinoma (HCC) tissues and that high levels of TMEM88 predict better overall survival." (PMID 37936608, 2023).
thyroid cancer (3 papers, 2022 to 2023). "The results of tumor formation experiments in nude mice also suggested that TMEM88 overexpression can significantly inhibit the growth of thyroid cancer, which is associated with the downregulation of active β-catenin expression." (PMID 35734592, 2022). "For example, low TMEM88 expression was identified in both thyroid cancer specimens and corresponding cell lines." (PMID 37091140, 2023). "A similar study reported low levels of mRNA and TMEM88 protein in thyroid cancer tissues compared to adjacent healthy tissues, as well as in thyroid cancer cell lines BCPAP, TPC1, K1, and NPA87 relative to the control cell line Nthy- Ori-3-1." (PMID 37936608, 2023). "Overexpressing TMEM88 remarkably attenuated proliferation and invasion capacities of thyroid carcinoma cells." (PMID 37091140, 2023). "In one study, the researchers found that TMEM88 was significantly reduced in thyroid cancer by analyzing the gene expression profile interactive analysis database." (PMID 35734592, 2022). "In contrast, depletion of TMEM88 can accelerate the proliferation and invasion ability of thyroid cancer cells." (PMID 35734592, 2022). "Various experimental methods, such as Western blotting, qRT-PCR, cell counting kit-8 assay and colony formation experiments, found that restoration of TMEM88 by vector transfection can markedly suppress the proliferation, colony formation and invasion ability of thyroid cancer cells." (PMID 35734592, 2022).
glioma (2 papers, 2023). A benign or malignant brain and spinal cord tumor that arises from glial cells (astrocytes, oligodendrocytes, ependymal cells). "In contrast, the TMEM88 gene was found to be a protective factor against glioma in the present study." (PMID 37064154, 2023).
invasive breast ductal carcinoma (2 papers, 2015 to 2022). "In contrast, TMEM88 was moderately expressed in carcinomas in situ and highly expressed in invasive ductal carcinomas (IDCs); however, the rate of positive expression was significantly higher in IDCs (71.22%, 99/139) than in normal breast ductal epithelium (11.4%, 4/35; p < 0.001)." (PMID 26325443, 2015).
lung adenocarcinoma (2 papers, 2019 to 2023). A carcinoma that arises from the lung and is characterized by the presence of malignant glandular epithelial cells. "Interestingly, overexpression of TMEM88 in lung adenocarcinoma cells also reduced TMEM88 expression and enhanced cancer cell proliferation and invasion, suggesting the possible regulating manner in HCC." (PMID 37091140, 2023).
lymph node metastasis (2 papers, 2015 to 2022). "We also detected nuclear localization of TMEM88, and determined that this localization pattern primarily occurred in triple-positive breast cancer tissues, where it negatively correlated with lymph node metastasis." (PMID 26325443, 2015). "Meanwhile, nuclear localization of TMEM88 was negatively correlated with lymph node metastasis (p = 0.046)." (PMID 26325443, 2015). "Furthermore, cytosolic TMEM88 expression correlated with advanced TNM stage and lymph node metastasis." (PMID 26325443, 2015). "However, cytosolic localization of TMEM88 was positively correlated with lymph node metastasis and TNM stage in triple-negative, but not triple-positive breast cancer tissues." (PMID 26325443, 2015). "In addition, the study also found that the cytoplasmic localization of TMEM88 was positively correlated with advanced TNM stage (P = 0.038) and lymph node metastasis (P = 0.01), while nuclear localization was inversely related to lymph node metastasis (P = 0.046)." (PMID 35734592, 2022).
cholangiocarcinoma (1 paper, 2023). A carcinoma that arises from the intrahepatic biliary tree (intrahepatic cholangiocarcinoma) or from the junction, or adjacent to the junction, of the right and left hepatic ducts (hilar cholangiocarcinoma). "Interestingly, the non-paired data showed that TMEM88 expressed higher in cholangiocarcinoma and HCC compared to nontumorous specimens." (PMID 37091140, 2023).
colorectal cancer (1 paper, 2025). A primary or metastatic malignant neoplasm that affects the colon or rectum. "In a comparative analysis, Noxa1 was primarily expressed in colorectal cancer tissues, Tmem88 was more prevalent in normal tissues, and Larp6 showed no significant expression differences between the two." (PMID 40084254, 2025).
deep venous thrombosis (1 paper, 2025). "We found significant associations between eQTL-mediated changes in TMEM88, NDRG2 and FZD5 expression with myocardial and vascular traits including heart rate and deep venous thrombosis." (PMID 39904980, 2025).
liver disease (1 paper, 2020). "Based on the function of TMEM88, research on targeted drugs of TMEM88 for liver disease will be subsequently carried out." (PMID 32463570, 2020). "Understanding the effects of TMEM88 on inflammation, autophagy, oxidative stress and other functions during liver fibrosis is a meaningful work, which can provide a bright future for the treatment of liver disease." (PMID 32463570, 2020).
liver fibrosis (1 paper, 2020). "The current research was for evaluating the function of TMEM88 in the process of the liver fibrosis and clarifying the inherent mechanism." (PMID 32463570, 2020). "Since the significant function of β‐catenin in liver fibrosis, it is urgent to study the TMEM88 mechanism in liver fibrosis." (PMID 32463570, 2020). "To summarize, our data indicated that TMEM88 is essential for the development of liver fibrosis and HSCs activation regulated by Wnt/β‐catenin signalling pathway in TGF‐β1‐stimulated LX‐2 cells." (PMID 32463570, 2020). "In future research, we will focus on the more features of TMEM88 in the development of liver fibrosis." (PMID 32463570, 2020). "The purpose of this study is to find the character of TMEM88 in liver fibrosis with the secretion of ECM proteins and cell activation and to elucidate the mechanism underlying the correlation between TMEM88 and Wnt/β‐catenin signalling pathway in HSCs." (PMID 32463570, 2020). "In summary, these results determined that TMEM88 might regulate the process of the liver fibrosis by Wnt/β‐catenin signalling pathway." (PMID 32463570, 2020). "Hereof, it is central to investigate the function of TMEM88 in liver fibrosis progression." (PMID 32463570, 2020). "Based on these observations, the role of TMEM88 in the progression of liver fibrosis remains unclear and needs further exploration." (PMID 32463570, 2020).
neuropathic pain (1 paper, 2023). Chronic pain caused by damage to nerve fibers. "TMEM88 codes for target transmembrane protein 88, which was upregulated in the SNL model (fold change = 1.33, p = 0.016) and in neuropathic pain patients (fold change = 1.56, Bonferroni-corrected p = 0.00038)." (PMID 36422814, 2023).
Pain (1 paper, 2023). An unpleasant sensory and emotional experience associated with actual or potential tissue damage, or described in terms of such damage. "TMEM88 is a known inhibitor of the Wnt/β-catenin canonical pathway, which is involved in neural development and plasticity in embryogenesis and in adult brains, and has been implicated in the production of hyperalgesia and allodynia in rat models of neuropathic pain." (PMID 36422814, 2023).